OAS1 (2'-5'-oligoadenylate synthetase 1)
Diseases named in the same sentence as OAS1 in open-access papers (continued):
Sharing a sentence is not in itself a finding about the gene and the disease.
tumor (continued). "Further studies revealed that high OAS1 expression was correlated with a poor prognosis in multiple tumor types, including ACC, LGG, LIHC, LUAD, PAAD, PRAD, and UVM." (PMID 37746262, 2023). "We further used the UALCAN database to explore OAS1 protein expression levels in tumor tissue and the corresponding normal tissue." (PMID 37746262, 2023). "The correlation between OAS1 expression and tumor immune microenvironment was finally investigated across various tumor types." (PMID 37928544, 2023). "Our study initially provides evidence that OAS1 plays a significant role across multiple tumor types." (PMID 37928544, 2023). "Our subsequent studies will incorporate experimental research to enhance our understanding of the role of OAS1 in tumor immunity." (PMID 37928544, 2023). "There is still a significant knowledge gap regarding how OAS1 specifically influences M2 macrophages and their impact on tumor immune evasion and immunotherapeutic resistance." (PMID 37928544, 2023). "We further examined the expression levels of OAS1 in tumor patients with different molecular subtypes in pan-cancers." (PMID 37746262, 2023). "According to research, OAS1 is significantly downregulated in BLCA tissues, and this downregulation is linked to the clinical characteristics and prognosis of the tumor." (PMID 38103068, 2023). "Our study has provided preliminary insights into the impact of OAS1 on tumor development from a bioinformatics perspective." (PMID 37928544, 2023). "In BRCA, HNSC, HUAD, THCA, and UCEC, tumor tissues show higher expression level of OAS1 than that in normal tissues, but OAS1 was lower in tumor tissues than that in normal tissues in COAD." (PMID 37746262, 2023). "We observed a small cluster of tumor cells (c9) that exhibited a gene expression pattern (OAS1, ISG15, OAS2) consistent with an interferon (IFN) response gene signature." (PMID 37609233, 2023). "Meanwhile, in order to comprehensively analyze the expression of OAS1 in pan-cancer, the expression level of OAS1 in tumor tissues and matched normal tissues were also examined using TCGA database." (PMID 37746262, 2023). "This study added a new dimension to our comprehensive understanding of OAS1 in tumor initiation and progression, and provided bioinformatics evidence and experimental evidence for application of OAS1 as a target gene in clinical tumor therapy in the future." (PMID 37746262, 2023). "Our findings indicate a strong correlation between OAS1 expression and macrophage infiltration in the tumor microenvironment across various types of cancer, as demonstrated by analyses of both bulk transcriptome data and single cell transcriptome data." (PMID 37928544, 2023). "OAS1 expression is related to AZA sensitivity in the NCI-60 set of tumor cell lines, suggesting that the level of OAS1 can be a biomarker for predicting AZA sensitivity of tumor cells." (PMID 36162993, 2022). "It highlights the key role of OAS1 in tumor immune infiltrating cells, neutrophils, and dendritic cells." (PMID 35898870, 2022). "OAS1 is an interferon-induced protein that synthesizes adenosine oligomers from ATP to prevent tumor growth and cell differentiation." (PMID 36468020, 2022). "We also evaluated the relations between OAS1 expression and tumor-infiltrating lymphocytes (TILs) in the TISIDB database." (PMID 35898870, 2022). "Because OAS1 is strongly associated with HCV infection and tumor prognosis, it is reasonable that there is a correlation between changes in methylation in noncancerous liver tissue and MO." (PMID 39132059, 2022). "TINCR combines with STAU1 to guide STAU1 to regulate the stability of OAS1, and low levels of OAS1 aggravate tumor proliferation and migration." (PMID 35756659, 2022). "We found that OAS1 was broadly expressed in different human organs and tumor tissues, with low organ and cancer specificity." (PMID 35082790, 2021).
tumor (continued). "miR-190 is involved in the regulation of several tumor suppressor genes, including CASP1, IFI6, IFITM2 and OAS1, which are associated with the induction of cell apoptosis and interferon response pathways." (PMID 37304648, 2021). "OAS1 showed a broad expression in different human organs and tumor tissues of the HPA database, with low organ and cancer specificity." (PMID 35082790, 2021). "Conversely, restoring IFN-β expression in OSM-expressing TNBC cells restored the expression of select ISGs (including STAT1, STAT2, IRF9, SOCS1, MX1, and OAS1 and reduced tumor sphere formation and tumor-initiating capacity." (PMID 31036052, 2019). "Given the role of OAS1 in immune regulation, further investigation into its involvement in the tumor microenvironment could have implications for immunotherapy strategies." (PMID 40303978, 2025). "Studies have found that OAS1 is highly expressed in many tumours." (PMID 41584451, 2025). "OAS1 expression was up-regulated in 12 tumor types and down-regulated in 2 tumor types." (PMID 37746262, 2023). "Finally, we only performed a functional enrichment analysis, and we did not use the in vitro and in vivo experiments to verify the functions of OAS1 in each tumor type." (PMID 37746262, 2023). "Notably, OAS1 expression exhibits significant differences between tumor and normal tissue, and it shows significant correlation with tumor staging within BLCA, PAAD, LUAD, SKCM, highlighting its potential as a prognostic marker." (PMID 37928544, 2023). "It is worth noting that the expression level of OAS1 in BLCA normal tissue was significantly higher than that in cancer tissue, which may suggest that OAS1 acts as a tumor suppressor gene in BLCA." (PMID 37746262, 2023). "All these findings suggest that OAS1 may play a pivotal role in cancer development, especially in regulating the tumor immune microenvironment." (PMID 37928544, 2023). "Our findings suggest that OAS1 could serve as a promising biomarker for predicting tumor immune infiltration and response to immunotherapy, especially M2 macrophage polarization." (PMID 37928544, 2023). "This suggests that OAS1 may also contribute to immune evasion of tumor cells by influencing M2 macrophages." (PMID 37928544, 2023). "In addition, the PML‐NB‐associated proteins, ISG20, OAS3, OAS1, and OASL were found to be upregulated and are considered to be tumour suppressors involved in promoting DNA cleavage, nuclear condensation, and apoptosis." (PMID 36579897, 2023). "OAS1 was correlated with molecular subtypes in 8 tumor types and immune subtypes in 12 tumor types." (PMID 37746262, 2023). "OAS1 may affect the anti-tumor immune response by regulating the expression of immune checkpoint genes." (PMID 37746262, 2023). "Therefore, more extensive pan-cancer studies are needed to gain comprehensive insights into the mechanisms through which OAS1 impacts tumor development and contributes to resistance against immunotherapy." (PMID 37928544, 2023). "OAS1 was upregulated in 12 tumor types and downregulated in 2 tumor types." (PMID 37746262, 2023). "We emphasize the potential role of OAS1 in tumor immune evasion and immunotherapeutic resistance." (PMID 37928544, 2023). "We found that OAS1 expression was positively correlated with tumor immune score, stromal score, and ESTIMATE score in most tumors, indicating a significant association with tumor immune infiltration." (PMID 37928544, 2023). "Moreover, the immune-related database was used to analyze the relationship between OAS1 and tumor microenvironment." (PMID 35898870, 2022). "OAS1 was underexpressed in NSCLC tumor B cells and PBL T cells." (PMID 35804895, 2022). "Notably, the expression level of OAS1 in normal BLCA tissues was significantly higher than that in cancerous tissues, suggesting that the OAS1 gene may function as a tumor suppressor in BLCA." (PMID 41584451, 2025). "Studies showed that OAS1 could survive through DNA damage preventing the death of tumor cells." (PMID 38380081, 2024).
tumor (continued). "Furthermore, the degree of OAS1 copy number variation could indicate tumor prognosis, suggesting potential implications on tumorigenesis and tumor progression." (PMID 37928544, 2023). "Current research suggests that OAS1 may be correlated with tumor prognosis in certain cancers." (PMID 37928544, 2023). "Therefore, OAS1 can be used to predict the therapeutic effect of tumor immunotherapy." (PMID 37746262, 2023). "Moreover, some reports have showed that OAS1 is involved in the regulation of tumor cell apoptosis." (PMID 37746262, 2023). "Interestingly, neutrophils exhibited the highest correlation with OAS members (cor = 0.268 in OAS1; cor = 0.42 in OAS2; cor = 0.371 in OAS3; cor = 0.332 in OASL), highlighting the key role of OAS members associated with neutrophils in tumor immune infiltrating cells." (PMID 32560641, 2020). "IFI6, IFI27, OAS1, and OAS3 are part of the interferon-alpha response (IFN-α) pathway, known for its anti-tumor and anti-viral immune responses." (PMID 39809731, 2025). "The upregulation of OAS1, OAS3, and IFITM1 expression in various tumor cell lines is observed following multi-fraction irradiation." (PMID 38473966, 2024). "The results showed that the expressions of YTHDC2, OAS1, and IFIT2 were all reduced in tumor tissues, whereas the expression of RAB5A was increased in tumor tissues." (PMID 39303913, 2024). "We selected four ISGs, OAS1, ISG15, MX1 and IFI6, for further validation by Taqman Q-RT-PCR in the HCC tumor tissues." (PMID 37686559, 2023). "In order to explore the correlation between OAS1 and tumor immune subtypes, the TISIDB database was used to explore the expression of OAS1 in different immune subtypes of pan-cancers." (PMID 37746262, 2023). "Among the identified DE genes in NSCLC PBL T cells and tumor T cell clusters, HLA-DRA, HLA-DRB1, OAS1, and CD74 had concordant prognostic indications at the mRNA and protein expression levels in bulk NSCLC tumors with resectable disease." (PMID 35804895, 2022). "VPS9D1-AS1 knockout downregulated OAS1, an ISG gene, which further reduced IFNAR1 levels in tumor cells." (PMID 36458816, 2022). "Multiple genes (HLA-DRA, HLA-DRB1, OAS1, and CD74) differentially expressed in NSCLC B cells, peripheral blood lymphocytes, and tumor T cells had concordant prognostic indications at the mRNA and protein expression levels." (PMID 35804895, 2022). "To further delineate the upstream pathway essential for IFNAR1 upregulation in tumor cells, we applied the CRISPR/Cas9 technique to abolish OAS1 expression." (PMID 36458816, 2022). "Hence, OAS1 may play a carcinogenic or tumor suppressor role, affecting the development of cancers." (PMID 35898870, 2022). "First, the biological functions of MET, OAS1, and OASL such as their interactions with immune cells in tumor microenvironment need to be explored in vitro experiments." (PMID 33869254, 2021). "Among these genes, there was few studies reported that OAS1 and IFI44 were related to tumor progression." (PMID 32241279, 2020). "Among these gene promoters are those involved in tumor suppression (RYBP, APEX, SST, OAS1) as well as oncogenes involved in positively aiding tumor progression (ARGH, FHX)." (PMID 23704879, 2013). "An interferon gene signature was also present in the profiles derived from the tumor epithelium of the ER-positive tumors (e.g., STAT1, IFIT1, IFIH1, IFI27, ISG15, OAS1, OAS3, OASL) and ER-negative tumors (e.g., HLA-DQA1 and HLA-DQB1)." (PMID 19225562, 2009). "Previous studies also reported that IFI44L, TRIM22, OAS1, OAS2, and MX2 inhibited tumor proliferation and metastasis, indicating that the transcriptional regulation of STAT1/2 could limit the development of OS." (PMID 40956299, 2025). "Also, we identified novel predicted tumor-suppressive ligands (SLIT3, DCN, CCN3, THBS1, INHA and INHBA), proteins (DNASE1L3, SULF1, PTEN, OAS1, and DAB2IP), and receptors (P2RX4, CDHR2, PTPRJ, and PTPRH) in MSC1 cells." (PMID 40564222, 2025).
tumor (continued). "OAS1 was overexpressed in C13 CD4 T cell clusters /C4-GZMK/C4-CD69 CD8/CD4 T cell clusters and suppressive tumor Tregs of CD4-C9CTLA cells vs. other tumor-infiltrating Tregs of CD4-C8-FOXP3 cells." (PMID 35804895, 2022). "Despite our findings showing no strong correlation between OAS1 expression and tumor neoantigen formation, with the exception of KIRP, READ, and SKCM, further research is required to elucidate the efficacy of OAS1 expression and immune checkpoint blockade therapy within specific tumors." (PMID 37928544, 2023). "This is probably because OAS1 may act as a tumor suppressor gene in other biological processes, such as cell proliferation, metastasis and drug resistance in BLCA, although OAS1 protects an immunosuppressive TME in BLCA, and these guesses need to be verified in the future." (PMID 37746262, 2023). "Thus, MET, OAS1, and OASL were distinctly correlated to tumor immune microenvironment." (PMID 33869254, 2021). "The TNM stage of patients may be easy to obtain, while the acquisition of another predictor (risk score) required knowledge of the expression of four immune-related genes (MAL, MS4A1, OAS1, and WFDC2) in tumor tissues, which undoubtedly increased the burden of nomogram application." (PMID 32850406, 2020). "In our PPI analysis, the majority of the genes in the most closely connected module were significantly upregulated in M1 macrophages, including STAT1, OAS1, OAS2 and DDX5; thus, developing small molecule agonists for these proteins may enhance anti-tumor immunity." (PMID 33323552, 2020). "Therefore, the high expression of OAS1 in tumor cells is likely to amplify IFN signaling and sustains a high level of ISG expression, then upregulate of immune checkpoint molecules, leading to T-cell exhaustion, immune escape and immunotherapeutic resistance of the tumor." (PMID 37928544, 2023). "Our analyses showed that both tumor and nontumor cells expressed IFN signaling genes such as STAT1, STAT2, ISG15, OAS1, and MX1 in all three datasets." (PMID 34771447, 2021). "Spearman correlation analysis showed a strong negative correlation between the effect of oHSV1-FLT3L on the rank-based AUC of the tumor cell growth and expression of RIG-I (r = −0.6727; p = 0.0277), ISG15 (r = −0.6909; p = 0.0226), and OAS1 (r = −0.6636; p = 0.0306; data not shown)." (PMID 40955425, 2025).
cancer (48 papers, 2007 to 2025). A tumor composed of atypical neoplastic, often pleomorphic cells that invade other tissues. "TIMER2, Kmplot, UALCAN, and TISIDB tools were used to investigate the expression and function of OAS1, and the role of OAS1 in prognosis, diagnostic value, and immune characteristics of pan-cancer." (PMID 37746262, 2023). "We note that OAS1 expression in 12 cancer types was significantly associated with different immune subtypes." (PMID 37746262, 2023). "Recent studies have shown that elevated OAS1 is associated with short survival in many cancers, and it is an important biomarker of poor prognosis." (PMID 35898870, 2022). "OAS1 has also been recently implicated in cancer cell survival after treatment with DNA damaging agents and in mediating the cytotoxicity of 5-azacytidine (AZA), a DNA methyltransferase inhibitor widely used in cancer treatment." (PMID 32678884, 2020). "We note that other SNPs associated with CIN3/cancer included those in the OAS1, OAS2, and POLN genes." (PMID 20084279, 2010). "This strengthens the hypothesis that immune-related mechanisms contribute to CRC susceptibility and that OAS1 may serve as a key genetic link between cancer and inflammatory pathways." (PMID 40303978, 2025). "ROC curves were used to evaluate the diagnostic value of OAS1 in pan-cancer." (PMID 37746262, 2023). "In addition, single nucleotide polymorphisms of OAS are associated with cancer, such as OAS1 SNP rs2660 AA." (PMID 30881302, 2019). "We found that cancer cells with lower levels of Lsd1 or higher levels of Oas1 or Oas3 were significantly more dependent on CFLAR." (PMID 38280853, 2024). "Recent research has shown that OAS1, as a member of the interferon-associated DNA damage resistance signature (IRDS), can enable cancer cells to survive DNA damage by attenuating PAR synthesis and preventing cell death." (PMID 37928544, 2023). "To better understand the role of OAS1 in cancer, we analyzed its expression changes in The Cancer Genome Atlas (TCGA) database, which contains descriptions of 33 types of cancer." (PMID 37928544, 2023). "We used multiple databases, including TCGA, UALCAN, GEPIA, TIMER2, and TISIDB, to comprehensively evaluate the effect of OAS1 in prognosis and immune response in pan-cancer." (PMID 37746262, 2023). "This study systematically investigated the correlation of OAS1 expression level with the prevalence and prognostic value at the pan-cancer level." (PMID 37746262, 2023). "We observed that the expression levels of OAS1 were different in diverse molecular subtypes of eight cancer types." (PMID 37746262, 2023). "GSEA_GO annotation was used to assess the OAS1-related signaling pathways that were differentially activated in pan-cancer." (PMID 37746262, 2023). "This discovery offers novel insights into potential therapeutic interventions, emphasizing the need for further research into the regulatory role of OAS1 in various cancer types." (PMID 37928544, 2023). "We also investigated the alternative splicing events of OAS1 gene and discovered a significant correlation between tumorigenesis and OAS1_alt_3prime_56568 in various cancers such as LUAD, STAD, UCS, BRCA, CESC, and SKCM." (PMID 37928544, 2023). "The expression, prognostic value, genetic alteration, alternative splicing events of OAS1 in pan-cancers were analyzed using TCGA, GTEx, HPA, GEPIA and OncoSplicing databases." (PMID 37928544, 2023). "To assess the relationship between OAS1 expression and other genomic alterations commonly observed in cancer that impact patient prognosis and treatment response, we compared TMB, MSI, and neoantigens at the pan-cancer level." (PMID 37928544, 2023). "This study suggests that OAS1 is a promising biomarker for the diagnosis and prognosis in pan-cancer, and can serve as a potential molecular target for multiple cancers." (PMID 37746262, 2023).